NOC2L (NOC2 like nucleolar associated transcriptional repressor)
Description:
Associates together with TP63 isoform TA*-gamma to the p21/CDKN1A promoter.
Synonyms: NIR; DKFZP564C186; NET7; NET15; PPP1R112
Tractability: Small molecule: a structure with a bound ligand is known. PROTAC: ubiquitination databases record sites on it; its protein half-life has been measured.
Gene: Protein-coding gene on chromosome 1 (943,527 to 960,714, reverse strand). Ensembl gene ENSG00000188976.
Subcellular location: Nucleus, nucleoplasm; Nucleus, nucleolus
Subcellular location (Human Protein Atlas): Mitotic chromosome; Nucleoli; Nucleoli rim
Gene Ontology:
Molecular function: chromatin binding; DNA-binding transcription factor binding; histone binding; nucleosome binding; protein binding; RNA binding; transcription corepressor activity
Biological process: cellular response to UV; negative regulation of B cell apoptotic process; negative regulation of intrinsic apoptotic signaling pathway; negative regulation of transcription by RNA polymerase II; transcription initiation-coupled chromatin remodeling; ribosomal large subunit biogenesis
Cellular component: chromosome; nucleolus; nucleoplasm; nucleus; Noc1p-Noc2p complex; Noc2p-Noc3p complex
Genetic constraint (gnomAD): Loss-of-function variants: 98 observed, 86.23 expected, observed/expected ratio (o/e) 1.14, 90% interval 0.96 to 1.34. The synonymous counts are far from expectation, so gnomAD's model fits this gene poorly and the ratio says little. Missense variants: 1,046 observed, 933.16 expected, observed/expected ratio (o/e) 1.12, 90% interval 1.07 to 1.18. Synonymous variants: 522 observed, 393.45 expected, observed/expected ratio (o/e) 1.33, 90% interval 1.23 to 1.43.
Homologues: Orthologues: chimpanzee NOC2L (98% identical), macaque NOC2L (93% identical), pig NOC2L (78% identical), guinea pig NOC2L (77% identical), dog NOC2L (77% identical), mouse Noc2l (75% identical), rat Noc2l (74% identical), rabbit NOC2L (64% identical), zebrafish noc2l (54% identical), Drosophila melanogaster Noc2 (34% identical), Caenorhabditis elegans pro-2 (23% identical).
Diseases named in the same sentence as NOC2L in open-access papers:
NOC2L is named in the same sentence as 16 diseases in open-access papers, as found by Europe PMC text mining. Sharing a sentence is not in itself a finding about the gene and the disease. The quoted sentences say what the papers report.
breast carcinoma (2 papers, 2017 to 2023). "In breast cancer cells, cell proliferation and colony formation was suppressed upon NOC2L knockdown, indicating an important role of NOC2L in breast cancer progression." (PMID 36650543, 2023). "NOC2L was demonstrated to be upregulated in breast cancer patients." (PMID 36650543, 2023). "Additionally, the NOC2L gene has been identified as a member of a group of prognostic genes derived from an integrated microarray of breast cancer studies." (PMID 28912426, 2017). "NOC2L was found to be recruited by Enhancer of zeste homolog 2 (EZH2) and cooperate with EZH2 through physical interaction to promote the methylation of H3K27 in the vicinity of forkhead box O3 (FOXO3) promoter region, leading to the downregulation of tumor suppressor FOXO3 in breast cancer cells." (PMID 36650543, 2023).
gastric cancer (1 paper, 2024). A primary or metastatic malignant neoplasm involving the stomach. "NOC2L is considered an inhibitor of the histone acetyltransferase (INHAT) and a proto-oncogene, with increased expression in most cancer tissues including gastric cancer." (PMID 39726754, 2024).
kidney cancer (1 paper, 2025). Primary or metastatic malignant neoplasm involving the kidney. "These distinct patterns suggest a possible dual behavior of the NOC proteins in kidney cancers – whereas CEBPZ and NOC3L might function cooperatively, NOC2L might act independently or even antagonistically in certain contexts." (PMID 40827841, 2025). "Among kidney cancer subtypes, chromophobe renal cell carcinomas (KICH) showed consistently and significantly reduced expression levels of CEBPZ, NOC2L and NOC3L, whereas other subtypes, such as KIRC (clear cell) and KIRP (papillary), displayed more variable expression patterns." (PMID 40827841, 2025).
kidney chromophobe carcinoma (1 paper, 2025). "Expression profiling across diverse tumor types revealed distinct patterns for CEBPZ, NOC2L and NOC3L, with them being elevated in several cancers, yet markedly reduced in AML and kidney chromophobe carcinoma (KICH)." (PMID 40827841, 2025).
Noonan syndrome (1 paper, 2026). Noonan Syndrome (NS) is characterized by short stature, typical facial dysmorphism and congenital heart defects. "LZTR1 attenuation resulting from genetic mutations associated with Noonan syndrome, potentiate NOC2L activity leading to reduced apoptosis and a compensatory increase in autophagy." (PMID 41175093, 2026).
cancer (6 papers, 2020 to 2025). A tumor composed of atypical neoplastic, often pleomorphic cells that invade other tissues. "In both cell and mouse xenograft, NOC2L has been demonstrated to promote tumor growth and cancer cell proliferation through RB, confirming its role in tumorigenesis of CRC." (PMID 36650543, 2023). "It has been proposed that NOC2L can participate in some key biological events, including the rRNA biogenesis, embryonic development, and cancer progression." (PMID 36650543, 2023). "We found that NOC2L increased in most cancer tissues than their counterpart, suggesting that it may be an oncogene." (PMID 36650543, 2023). "Analysis of gene essentiality in 517 cancer cell lines (including 53 OC cell lines) show that PTMA, INTS1, and NOC2L are all common essential genes in cancer." (PMID 32332753, 2020).
tumor (4 papers, 2017 to 2025). "Depletion of NOC2L in LOVO tumor cells inhibits their growth in xenograft mice, supporting a role in tumor progression." (PMID 40827841, 2025). "We analyzed the expression across diverse tumor types based on the hypothesis that CEBPZ, NOC2L and NOC3L form regulatory heterodimers that modulate this process." (PMID 40827841, 2025).
NOC2L also shares sentences with these, for which no sentence is quoted: lung adenocarcinoma (2 papers); adenoid cystic carcinoma (1); Cerebral degeneration (1); heart diseases (1); infection (1); Iron deficiency (1); pancreatic cancer (1); preeclampsia (1); rectum adenocarcinoma (1).